KRAS (KRas proto-oncogene, GTPase)
Diseases named in the same sentence as KRAS in open-access papers (continued):
Sharing a sentence is not in itself a finding about the gene and the disease.
cancer (continued). "Crosstalk activation of the PI3K pathway via signalling through KRAS as well as mutations in PIK3CA and PTEN that occur in 17% and 21% of BRAF mutant cancers, respectively, can render cancer cells resistant to MAPK inhibition." (PMID 30598662, 2018). "Here, by exploring vulnerabilities of human tumors that depend on mutant KRas, we sought to identify kinases and their corresponding pathways that mutant KRas depends on to induce malignant transformation and to target such pathways for cancer therapy." (PMID 30514931, 2018). "Here we show for the first time that KRAS-mutant cancer cells display altered NF-κΒ utilization in resting and stimulated states, a phenomenon previously identified in pancreatic β cells." (PMID 29445180, 2018). "With the advent of novel therapies targeting the epidermal growth factor receptor (EGFR), the focus once again shifted to KRAS as a predictor of response to cancer therapy." (PMID 30283732, 2018). "It is also known that activation of the PI3K pathway mediates resistance to MEK inhibitors in KRAS-mutant cancers." (PMID 29697368, 2018). "As a result, we identified eight common mutated genes (EBAG9, MTDH, ATP6V1C1, OPA1, ATCL6A, BCL6, SENP5, KRAS) in the three different cancer types and used them as cross-cancer biomarkers to perform an integrative network analysis." (PMID 29459674, 2018). "CUP adenocarcinomas and poorly differentiated carcinomas harboured the highest frequency of variants in genes involved in signal transduction pathways (e.g. MET, EGFR, HRAS, KRAS, and BRAF)." (PMID 29973234, 2018). "Despite these extensive efforts, KRAS remains largely undruggable for cancer therapy for the reasons including, but not limited to, pharmacological and biological constraints associated with this pathway." (PMID 29133857, 2017). "We reveal functional separation between resistance mechanisms and KRAS mutation status and demonstrate that drug-induced cytotoxicity of KRAS mutant cancer cells is contingent on MYC inhibition." (PMID 28152508, 2017). "Among thirty included studies, 12 studies and 29 studies which reported the association of KRAS mutation detected by cfDNA with OS and PFS in cancer patients respectively." (PMID 28796802, 2017). "Recent data suggest that insulin-like growth factor 1 receptor (IGF1R) exerts dominant control over PI3K signaling in human KRAS mutant cancers." (PMID 28152508, 2017). "Binding of Chelerythrine with BCL2, VEGFA and KRAS genes involved in evasion, angiogenesis and self sufficiency of cancer cells provides a new insight for the development of future therapeutics against cancer." (PMID 28102286, 2017). "Our results thus provide a foundation for scientific and clinical development of honokiol against KRAS-driven cancers." (PMID 28443025, 2017). "In the MAPK signaling pathways, the Raf/MEK/ERK cascade is activated by mutant KRAS and plays a crucial role in the regulation of cancer cell proliferation, differentiation, survival and migration." (PMID 29262632, 2017). "KRAS is one of the most common oncogenes involved in the multi-step process of cancer development, including cancer initiation, metastasis, and prognosis." (PMID 28398227, 2017). "An RNAi screen for factors whose depletion inhibits the growth of mutant KRAS G12D-expressing cancer cell lines identified PLK1 and components of the APC/C ubiquitin-conjugating holoenzyme." (PMID 28807782, 2017). "BCL2, KRAS and VEGFA, most frequently mutated oncogenes in human cancer are overexpressed in different types of human malignancies." (PMID 28102286, 2017).
cancer (continued). "Considerable efforts have been made to tackle the cancer driver KRAS, a bona fide oncoprotein that lacks clearly druggable cavities or grooves, and a number of early studies concluded that KRAS-mutant tumors become addicted to autophagy." (PMID 28697345, 2017). "Mutant KRAS promotes persistent activation of downstream effectors, leading to survival and proliferation of cancer cells mainly through the Ras/Raf/MEK/ERK pathway or PI3K/AKT pathway." (PMID 28451792, 2017). "KRAS mutation and amplification lead to an activation of the RAF-MEK-ERK pathway, which is critical to pathogenesis and progression in many cancers." (PMID 29089060, 2017). "We previously reported that a recombinant adenovirus, carrying a pro-apoptotic gene (PUMA) under the regulation of Ets/AP1 (RAS-responsive elements) suppressed the growth of cancer cells harboring hyperactive KRAS." (PMID 28445136, 2017). "These mutant KRAS or BRAF-driven cancers show a poorer response to chemotherapy and are negatively indicated for treatment with EGFR inhibitors." (PMID 28640835, 2017). "Here, the authors show that cancer cells with KRAS mutations promote MPE by recruiting myeloid cells via CCL2 signalling and that pharmaceutical targeting of KRAS results in reduced MPE incidence and volume in mouse models." (PMID 28508873, 2017). "Arguably, the role of the proto-oncogene MYC in drug resistance is one of the biggest unanswered questions concerning KRAS-driven cancers." (PMID 28152508, 2017). "Collectively, these data suggest that cancer cells can overcome poor KRAS expression by globally upregulating protein synthesis through mechanisms that also enable cancer cells to overcome the effects of codon bias." (PMID 28593995, 2017). "The RAS gene family members include HRAS, KRAS, and NRAS, with the latter two being the isoforms commonly mutated in cancers." (PMID 27650277, 2017). "Targeted genetic profiling of all polyps for 15 established cancer-associated genes (TruSight®Tumor15, Illumina) confirmed the BRAF V600E and KRAS G12D mutations in 5 (46%) and one (9%) polyps, respectively." (PMID 29213343, 2017). "In agreement with PLX-0012 profile, we observed a weak paradoxical induction in one out of eight KRAS-mutant cancer cell lines." (PMID 29084939, 2017). "Further studies will be required to evaluate the relative sensitivity of a wider range of normal and KRAS mutant cancer cells." (PMID 28806777, 2017). "Instead, the expression level of mutant KRAS is likely to be a second key contributor to resistance, a notion that directly implicates codon bias and the ability of cancer cells to adopt mechanisms that overcome the translational barrier it imposes." (PMID 28593995, 2017). "Many genes, such as Bcl-xl, kRAS, COX, iNOS, APC, Smad3, STAT3, Ptgs2, Tnfrsf6, p16, Mlh1, Runx3, Dapk, and β-catenin are mutated in stages of carcinogenesis of the UC-associated cancer." (PMID 28621756, 2017). "Our findings unveil KRAS downstream effectors that provide opportunities to treat KRAS-driven cancers." (PMID 28220783, 2017). "The application of another ASO (AZD4785) which targets the KRAS gene was demonstrated to diminish the proliferative activity of KRAS-driven cancer types." (PMID 29283381, 2017). "Lin-28B overexpression increased the expression of the HMGA2, c-MYC and KRAS genes, which are targeted by the cancer suppressor miRNA let-7." (PMID 28947981, 2017). "Consistent with a BRET profile similar to second-generation compounds, LY-3009120 induced pERK activation with variable potencies in each KRAS-mutant cancer cell line examined." (PMID 29084939, 2017). "Our data show that miR-29b antagonism is effective in restoring TSG expression in KRAS-activated cancer cells and identify cancer gene expression subtypes that rationalize AM-29b drug development." (PMID 29088821, 2017). "We identify MYC as a key component of this process and show that MYC plays an essential cell-intrinsic role in maintaining the survival of KRAS mutant cancer cells." (PMID 28152508, 2017).
cancer (continued). "Despite recent advances in personalized medicine and a better understanding of human cancers, targeting oncogenic drivers such as KRAS still remains a challenging issue in the cancer therapeutic armamentarium." (PMID 28173629, 2017). "We found that miR-31 and miR-135b were significantly up-regulated, while, miR-193a-3p was marginally significantly down-regulated (P = 0.09) in BRAF-mutant cancers compared to KRAS-mutant cancers." (PMID 29115941, 2017). "The mutations of RAS (KRAS and NRAS), IDH2, EGFR, and PI3K are clinically relevant and well associated in many other cancers." (PMID 28900470, 2017). "Our findings demonstrate that the effects of NRP1 knockdown in cancer cells are dependent on the genetic status of KRAS." (PMID 29018205, 2017). "A previous study has demonstrated that some KRAS-driven cancers cells significantly upregulate OXPHOS metabolism." (PMID 28852500, 2017). "Our GSEA analysis also indicates that GGT is significantly correlated with EMT, KRAS, SRC and PKCA pathways, which are closely associated with cancer metastasis and proliferation." (PMID 28404903, 2017). "Such cancer type–specific associations were also seen for PIK3CA, KRAS, GATA3, CTCF, CDH1, and ARIDA1." (PMID 29125844, 2017). "Cancer cells frequently respond to standard treatments by readjustment of signaling networks or through acquisition of bidirectional conversions between KRAS-dependent (drug-sensitive) and independent (drug-resistant) cell states." (PMID 28152508, 2017). "Our findings exemplify the utility of small molecules modulating the protein-protein interactions of PLKs to therapeutically target mutant KRAS-expressing cancers." (PMID 28807782, 2017). "By testing a range of potential therapeutic combinations, we demonstrate that analysis of compensatory pathway activation can facilitate design of synthetic lethal chemotherapeutic combinations to address KRAS‐mutant cancer." (PMID 28173629, 2017). "The investigators made several conclusions, first that the compensatory response involving FGFR1 appears specific to particular KRAS-mutant cancer histologies." (PMID 28030802, 2017). "Genetic modulation of the pathway linking PLK1 to APC/C activation curtailed the proliferation of mutant KRAS G12D-expressing cancer cells, while ATP-competitive PLK1 inhibitors suppressed their growth as xenografts." (PMID 28807782, 2017). "report the development of Poloppins, compounds that target the protein-protein interactions of human Polo-like kinases via their Polo-box domain, in monotherapeutic or combination strategies to treat KRAS-mutant cancers." (PMID 28807782, 2017).
cancer (continued). "When applied on 40 ng of DNA from fresh HCT116 cells, eight variants were detected, including KRAS (p.G13D), PIK3CA (p.H1047R), and CTNNB1 (p.S45del), with all of them being reported in ATCC or in COSMIC (Catalog of Somatic Mutations In Cancer)." (PMID 29263843, 2017). "The elucidation of the exact mechanism of action of our compounds in KRAS-dependent cancer cells will impact the search and characterization of inhibitors of KRAS and possibly other membrane-associated proteins." (PMID 28384226, 2017). "Our data support the notion that KRAS mutant cancer cells depend on the continued expression of MYC and drug-induced cytotoxicity of KRAS mutant cells is contingent on MYC inhibition." (PMID 28152508, 2017). "Activating KRAS mutations are associated with poor prognosis in patients with non-small cell lung cancers (NSCLCs), and KRAS mutant NSCLC tumors are often resistant to common anti-cancer drugs." (PMID 29267283, 2017). "Recently, the Wee1 inhibitor AZD1775 was identified as a potential agent for targeting mutant KRAS-expressing cancers." (PMID 28978051, 2017). "An optimized analog with favorable pharmacokinetics, Poloppin-II, is effective against KRAS-expressing cancer xenografts." (PMID 28807782, 2017). "Mutant KRAS expression is proposed to trigger abnormalities in progression through mitosis (“mitotic stress”) that render cancer cells sensitive to PLK1 inhibition." (PMID 28807782, 2017). "In this context, particularly interesting were the results of a study by Genovese and coworkers, based on the study of cancer cell plasticity in a conditional oncogenic KRAS model of PDAC." (PMID 29156578, 2017). "The fact that loss-of-function experiments demonstrated that FOSL1 is important in mutant KRAS LAC argues that the overall approach integrating gene-expression and survival data is successful to identify genes with a relevant role in KRAS-driven cancer." (PMID 28220783, 2017). "Here we report the identification of a common transcriptional signature across mutant KRAS cancers of distinct tissue origin that includes the transcription factor FOSL1." (PMID 28220783, 2017). "Considering KRAS also activates multiple other signaling pathways, identifying novel MEK inhibitor-based combination therapies with potential effectiveness in cancer cells with various concomitant mutations is therefore urgently needed." (PMID 28938614, 2017). "Concretely, we reveal and confirm that COPB2 is a synthetic lethal partner of KRAS and hence a promising cancer target." (PMID 28415695, 2017). "While both pre-clinical and clinical data have demonstrated that the virus is active and definitely so in KRAS mutant cancers, its mechanism of activity remains elusive." (PMID 28422714, 2017). "Many of these studies evaluated short peptide-based KRAS vaccines, overwhelmingly in patients with late-stage cancers." (PMID 29137294, 2017). "Although MYC is clearly required for the maintenance of KRAS-driven cancer, our data imply that the KRAS oncogene is inefficient in sustaining expression of MYC in the absence of growth factors or in response to anticancer drug treatment." (PMID 28152508, 2017). "To understand the differential role of NRP1 in tumorigenesis process, we utilized cells from two different cancer types, pancreatic and lung, each containing either wild type KRAS (KRASwt) or mutant KRAS (KRASmt)." (PMID 29018205, 2017).
cancer (continued). "Our data also distinguish a different SOX2 enhancer region accessible to NFATc2 which functions not only in the presence of KRAS mutation (A549, PDCL#24) but also in EGFR mutant (HCC827) cancers." (PMID 28737489, 2017). "KRas has long been a target for anti-cancer drug development, although many earlier strategies, including those targeting farnesyltransferase, have been disappointing." (PMID 29088764, 2017). "Poloppin and Poloppin-II act synergistically with Crizotinib, a clinically used inhibitor of the c-MET receptor, against mutant KRAS-expressing cancer cells, revealing an approach for combination therapy." (PMID 28807782, 2017). "Among the numerous potential targets of the miR-155, we focused on KRAS because of its key role in development and cancer." (PMID 28259135, 2017). "Our analysis of Ras isoform gene expression in normal tissues is broadly consistent with the dominance of KRas protein expression in cancer cell lines representing a wide range of tissues; however, the relative proportions are significantly different." (PMID 28117393, 2017). "In a recent large scale screening, MEK inhibitors were among the most effective agents in KRAS-mutant cancers, making MEK inhibitor a promising backbone for combination therapy." (PMID 28938614, 2017). "To this end we focused on CRC, a cancer in which oncogenic KRAS is well established to be a central driver of primary and acquired resistance to anti-EGFR therapies." (PMID 28593995, 2017). "Recent studies showed that K-Ras4a is widely expressed in human cancers, suggesting that K-Ras4a plays a significant role in KRAS-driven tumors." (PMID 29239724, 2017). "Since PDK1 comprises the most crucial effector downstream of KRAS, it is the best alternative for targeted therapy in this type of cancer." (PMID 29064423, 2017). "In sum, although MYC has traditionally been regarded to be a pro-apoptotic protein, drug-induced cytotoxicity of KRAS mutant cancer cells appears to depend on MYC inhibition." (PMID 28152508, 2017). "An optimized analog (Poloppin-II) is effective against KRAS-expressing cancer xenografts after systemic oral administration." (PMID 28807782, 2017). "It has been shown that KRAS and BRAF mutated cancer cells expressed more GLUT1 transporters that had led to increased uptake of vitamin C in its reduced form, dehydroascorbate (DHA)." (PMID 28791253, 2017). "We evaluated the cytotoxic effects of the currently accepted therapeutic agents (gemcitabine plus cisplatin) and novel targeted compounds (MEK, PI3K and HDAC inhibitors) on the drug sensitivity versus resistance of KRAS mutant and KRAS wild-type cancer cells." (PMID 28152508, 2017). "Current models posit that MYC is essential for KRAS-driven cancer; RAS activation stabilizes MYC; in turn, MYC renders cells vulnerable to DNA damage and apoptosis." (PMID 28152508, 2017). "We report here that Poloppin and Poloppin-II, compounds that target the protein-protein interactions of human Polo-like kinases, suppress the growth of KRAS-mutant cancer cells as single agents, or in combination with c-MET inhibitors." (PMID 28807782, 2017). "KRAS mutations, which affects both K-Ras4a and K-Ras4b, occur most frequently, accounting for 86% of RAS-driven cancers." (PMID 29239724, 2017). "In the two remaining cases (AB016 and AB017), the KRAS mutant population was at a subclonal frequency within the adenomatous region, with the carcinoma exclusively KRAS wild-type." (PMID 29222441, 2017). "In detail, the group of KRAS wildtype tumors (7.3%, 13/177) included conventional PDACs (7/13), combined PDACs (3/13), and one colloid, one medullary and one tubular carcinoma." (PMID 28145465, 2017). "To identify innovative drug combinations to treat KRAS-mutant cancers, we performed a synthetic lethal chemical screen." (PMID 27193833, 2016).